DCX (doublecortin)
Diseases named in the same sentence as DCX in open-access papers (continued):
Sharing a sentence is not in itself a finding about the gene and the disease.
brain injury (2 papers, 2021 to 2023). Acute and chronic (see also brain INJURIES, CHRONIC) injuries to the brain, including the cerebral hemispheres, CEREBELLUM, and brain STEM. "After three days of brain trauma, newborn DCX positive cells emigrated toward cerebral cortex lesion; however, co-ultra PEALut treatment clearly modulated DCX positive cells in the DG region." (PMID 34445417, 2021).
breast tumors (2 papers, 2022 to 2024). "Recent findings in mouse models of prostate and breast tumours have demonstrated that DCX + neural progenitors migrate from the CNS to primary and metastatic tumour sites." (PMID 39232464, 2024). "In summary, we identified DCX + cells in the stroma of breast tumours, and the presence of stromal DCX + cells was higher in basal-like BC and tumours with higher histological grade, based on our single-cell analysis." (PMID 39232464, 2024). "The presence of DCX + cells in the stromal compartment was associated with aggressive tumour features, with higher proportion of DCX + cells in breast tumours with increasing histological grade." (PMID 39232464, 2024). "To assess whether human primary breast tumours contain DCX-expressing cells, we used imaging mass cytometry (IMC) analysis to capture DCX-positive cells in the stromal compartment of basal-like and luminal-like breast tumours." (PMID 39232464, 2024). "To ensure that no potential cancer cell expression of DCX was included in our IMC analysis of breast tumours, we separated stromal from epithelial tissue compartments prior to focusing on the DCX + cell population." (PMID 39232464, 2024).
cerebral infarct (2 papers, 2020 to 2025). "As a reflect of regenerative neurogenesis, the number of DCX-positive neuroblasts migrating to the damage area was higher in the perilesional regions of db/db mice compared to db/+ ones, and appeared correlated to the size of cerebral infarct." (PMID 39816479, 2025).
colitis (2 papers, 2022 to 2025). Inflammation of the colon. "However, enhanced microglial cell activity in the hippocampus is correlated with a reduction in a neuronal marker, doublecortin (DCX), associated with reduced neurogenesis and behavioural abnormalities in mice with DSS-induced colitis." (PMID 34983592, 2022).
cortical dysplasia (2 papers, 2017 to 2024). "Targeted sequencing of multigene panels in next-generation sequencing for genes associated with cortical dysplasia highlighted the presence of the c.151A>G(p.(Met51Val)) variant in the DCX gene (MIM*300121) and c.1186G>A(p.(Val396Ile)) in the PAFAH1B1 gene (MIM*601545), both paternally inherited." (PMID 38790177, 2024). "The assessment of protein expression of a wide range of markers showed that the two patients with cortical dysplasia, included in this study, express higher percentages of several neuroblast and stem cell markers including DCX, NeuN, Nurr1, CD56, CD166, CD9, CD73, CD59, CD61 and cKit." (PMID 28796246, 2017).
epileptic seizures (2 papers, 2015 to 2025). "Many reports indicate that epileptic seizures can severely affect the number of DCX-positive cells, but the direction of these changes is strongly stage-dependent." (PMID 41516142, 2025).
fragile X syndrome (2 papers, 2023 to 2024). A genetic syndrome caused by mutations in the FMR1 gene which is responsible for the expression of the fragile X mental retardation 1 protein. "These spines’ morphological defects on DAP-treated DCX+ cells are reminiscent of those observed on mature neurons from mutant mice of the fragile X mental retardation protein (Fmr1) and from human patients’ brains that suffer from the fragile X syndrome." (PMID 36720500, 2023).
Hyperglycemia (2 papers, 2013 to 2019). An increased concentration of glucose in the blood. "We evaluated the expression of doublecortin and synaptophysin in the peri-infarct zone to study the role of hyperglycemia in neurogenesis and synaptogenesis." (PMID 31315686, 2019).
injury (2 papers, 2020 to 2023). Damage inflicted on the body as the direct or indirect result of an external force, with or without disruption of structural continuity. "Moreover, NIR-PBM can reduce cell death and improve learning and memory performance by increasing the expression of neuroprogenitor cells, doublecortin, and TUJ1 after controlled cortical impact or traumatic brain injury induction in mice." (PMID 37895108, 2023).
leiomyoma (2 papers, 2023 to 2024). A well-circumscribed benign smooth muscle neoplasm characterized by the presence of spindle cells with cigar-shaped nuclei, interlacing fascicles, and a whorled pattern. "Several studies suggested that DCX is correlated to cancer cells invasion and metastasis and is overexpressed in leiomyomas as well." (PMID 36835153, 2023). "Several other genes, although upregulated in non-mutated samples, showed a greater magnitude of increase in expression in the mutated leiomyoma group, including FN1, DCX, and COL11A1." (PMID 36835153, 2023). "Our data indicate that in addition to marked overexpression of DCX in leiomyomas, in both mutated and non-mutated tumors with greater increase in the mutated leiomyomas, the myometrium of MED12-mutated specimens also overexpressed DCX." (PMID 36835153, 2023). "This analysis indicated that the expression of WNT16, CACNA1D, DCX, and WIF1 was significantly higher, while the expression of MTMR8 was significantly lower in myometrium adjacent to MED12-mutated leiomyomas compared to myometrium adjacent to MED12 wild-type leiomyomas." (PMID 36835153, 2023).
malignant glioma (2 papers, 2021 to 2023). A grade III or grade IV glioma arising from the central nervous system. "Consistent with the glial nature of malignant gliomas, genes downregulated at T2 and End were enriched for neuronal differentiation and synaptic functions (e.g., DCX, NEUROD2, and SYN1)." (PMID 33390587, 2021). "Although TP mice had a lower malignant glioma penetrance, we observed a significant decrease of Ki67+DCX+mCherry+ cells and an increase of Ki67+OLIG2+mCherry+ cells among total Ki67+mCherry+ cells from T1 to T2." (PMID 33390587, 2021).
melanoma (2 papers, 2019 to 2025). A malignant, usually aggressive tumor composed of atypical, neoplastic melanocytes. "Protrusions of melanoma cells rich in GAP43, MARCKS, and doublecortin travel through white matter and frequently align with oligodendrocyte processes, which are physical guides for the movement of melanoma cells." (PMID 41463339, 2025).
meningioma (2 papers, 2019 to 2023). A generally slow growing tumor attached to the dura mater. "The role of E-cadherin, N-cadherin, β-catenin and doublecortin (DCX) have been evaluated in both canine and human meningiomas." (PMID 38137885, 2023). "This N-cadherin expression is joined by expression of doublecortin at the invading line of the meningioma as well as increased nuclear β-catenin, all three of which may hold prognostic value for more aggressive meningiomas." (PMID 31788444, 2019). "In canine tumors, N-cadherin, β-catenin, and DCX seem to have a positive correlation with invasion and anaplastic subtypes of meningiomas, instead in human meningiomas, it has not demonstrated a correlation and this role is still debated." (PMID 38137885, 2023).
pancreatic cancer (2 papers, 2022). "We did, however, detect DCX-expressing cells in pancreatic tumors." (PMID 35418199, 2022). "In response to knockdown of doublecortin and CaM kinase-like-1(DCAMKL-1), miR-144-3p level was increased, which in turn repressed pancreatic cancer EMT." (PMID 35568918, 2022).
prion disease (2 papers, 2016). A transmissible disease that is caused by a protein that is able to induce abnormal folding of normal cellular proteins, leading to characteristic spongiform brain changes, which are associated with neuronal loss without an inflammatory response. "The expansion of DCX+NPCs observed in ME7 mice was prevented when microglial proliferation was blocked, providing evidence that the role of microglia during prion disease was mainly pro-neurogenic." (PMID 26541819, 2016).
Sepsis (2 papers, 2019 to 2020). Sepsis is defined as life-threatening organ dysfunction caused by a dysregulated host response to infection. "In addition, sepsis downregulated the expression of neuronal markers for stem cells (nestin and BLBP), proliferation (Ki67), and differentiation (DCX)." (PMID 33100215, 2020). "Additionally, mouse models of sepsis have lower levels of glutamatergic NMDA receptors, as well as reduced numbers of doublecortin-positive newborn neurons and parvalbumin interneurons in the hippocampus." (PMID 31920505, 2019).
Tinnitus (2 papers, 2013 to 2024). Tinnitus is an auditory perception that can be described as the experience of sound, in the ear or in the head, in the absence of external acoustic stimulation. "The increase in the expression of DCX as a marker of neural plasticity in the three mentioned regions was an important finding that indicated the occurrence of plastic changes in tinnitus and also the role of these regions in the development of tinnitus." (PMID 38626075, 2024). "In the DCN, the expression of DCX in the tinnitus group was significantly higher than the control group (P = 0.006)." (PMID 38626075, 2024). "In the PFL, the expression of DCX in the tinnitus group was significantly higher than the control group (P = 0.0008) and in the PBMT group it was significantly higher than the control group (P = 0.005)." (PMID 38626075, 2024). "In the DG, the expression of DCX in the tinnitus group was significantly higher than the control group (P = 0.0004)." (PMID 38626075, 2024). "Harmful neural plasticity induced by tinnitus was detected by doublecortin (DCX) protein expression, a known marker of neural plasticity." (PMID 38626075, 2024). "In the PBMT group, the expression of DCX was significantly higher than the control group (P = 0.009), but it was significantly lower than the tinnitus group (P = 0.01)." (PMID 38626075, 2024). "An important finding was a significant increase in DCX expression in DCN, PFL, and DG in the tinnitus group." (PMID 38626075, 2024). "In addition, a significant increase in DCX expression in the dorsal cochlear nucleus (DCN), dentate gyrus (DG) and the parafloccular lobe (PFL) of cerebellum was observed in the tinnitus group." (PMID 38626075, 2024). "The difference in DCX expression between tinnitus and PBMT groups was not significant (P > 0.05)." (PMID 38626075, 2024). "The expression of DCX was not significantly different between tinnitus and PBMT group (P > 0.05)." (PMID 38626075, 2024).
tubulinopathies (2 papers, 2022 to 2024). "Subcortical band heterotopia has only been sporadically described in tubulinopathies, being more frequent in association with the genes DCX and LIS1." (PMID 35017693, 2022).
type 1 lissencephaly (2 papers, 2007 to 2014). "Together, mutations in DCX, LIS1, VLDLR, and reelin are responsible for ∼70% of the cases of type 1 lissencephaly." (PMID 17218254, 2007). "Among them, the Doublecortin (Dcx) MAP, also involved in type 1 lissencephaly, when inactivated in mouse generates a striking anatomical defect, mainly restricted in the CA3 region, with an abnormal double layer of pyramidal neurons." (PMID 24624057, 2014).
acute myeloid leukemia (1 paper, 2012). Acute myeloid leukemia (AML) is a group of neoplasms arising from precursor cells committed to the myeloid cell-line differentiation. "The reported tumor stem cell markers also included Aldehyde dehydrogenase (ALDH1), Musashi-1, LgR5, the prostate stem cell antigen (PSCA), Doublecortin and CaM kinase-like-1 (DCAMKL-1), and acute myeloid leukemia (AML) stem cell-surface marker TIM3." (PMID 22634835, 2012).
anaplastic oligodendroglioma (1 paper, 2016). A WHO grade III oligodendroglioma with focal or diffuse malignant morphologic features (prominent nuclear pleomorphism, mitoses, and increased cellularity). "Our gene signature also contained proneural genes, BMP2, DCX, IGFBP2, PDPN, and PLAT, which are associated with anaplastic oligodendroglioma harboring 1p/19q co-deletion." (PMID 27323413, 2016).
astrocytomas (1 paper, 2019). "Interestingly, we also found that some neuronal markers such as DCX, MAP2 and NeuN were highly expressed in astrocytomas." (PMID 31212628, 2019).
Ataxia (1 paper, 2020). Ataxia refers to impaired coordination of voluntary muscle movement. "CDNF improved motor coordination and decreased ataxia in QA-toxin treated rats, and stimulated the neurogenesis by increasing doublecortin (DCX)-positive and NeuN-positive cells in the striatum." (PMID 33154393, 2020).
Cirrhosis (1 paper, 2025). A chronic disorder of the liver in which liver tissue becomes scarred and is partially replaced by regenerative nodules and fibrotic tissue resulting in loss of liver function. "As in the rat, neurogenic netrin-1 expression was strongly (r >0.85) correlated with proteolyzed β-tubulin and DCX levels, as well as cirrhosis onset, and HCC." (PMID 39717507, 2025).
cyst (1 paper, 2014). A sac-like closed membranous structure that may be empty or contain fluid or amorphous material. "Small numbers of DcX and GAP43 positive fibres penetrated into tissue located within the cyst region, although these tended to be located immediately at the periphery of the cyst walls, and the number of fibres did not appear to differ between groups (data not shown)." (PMID 25105800, 2014). "Cyst size and morphological parameters, including the amount of degenerative tissue immediately surrounding the cyst, were assessed in toluidine blue stained sections and using immunohistochemical assessments of GFAP, β-III tubulin, DcX and GAP43 immunoreactivity at 28 days following SCI." (PMID 25105800, 2014).
demyelination (1 paper, 2020). "For this reason, the aim of the present study was to investigate whether DCX+ NPCs are able to replace lost oligodendrocytes in the hippocampal DG after cuprizone-induced demyelination." (PMID 33208869, 2020). "In the DCX reporter model, the numbers of GFP+ cells which were also labeled by Olig2 or Olig2 and CC1 were analyzed after 6 weeks of cuprizone treatment (demyelination group) which were followed by 2 weeks of normal chow (remyelination group) and compared to controls." (PMID 33208869, 2020). "In the present study, the demyelination group had the lowest number of DCX+ cells, this reduction was, however, not significant in comparison to the other groups." (PMID 33208869, 2020).
Dystonia (1 paper, 2015). An abnormally increased muscular tone that causes fixed abnormal postures. "By week 6 post-CCI, Mash1, DCX and Notch3 expression was significantly increased in the ipsilateral dorsal horns and in the ventral horns, suggesting that neurogenesis might also contribute to the motor abnormality (e.g. dystonia) associated with neuropathic pain." (PMID 26223362, 2015).
hippocampal atrophy (1 paper, 2025). "In addition, insulin prevents hippocampal atrophy neuronal loss, increasing neuronal density, doublecortin, PSD95 and BDNF levels." (PMID 41146261, 2025).
hyperopia (1 paper, 2008). A refractive error in which rays of light entering the eye parallel to the optic axis are brought to a focus behind the retina, as a result of the eyeball being too short from front to back. "Five of them were upregulated during induction of hyperopia with positive lenses (DCX, NLGN1, QSER1, TMTC3, and LOC41695) and one was downregulated (GRHL3)." (PMID 18769560, 2008).
Hypertension (1 paper, 2019). The presence of chronic increased pressure in the systemic arterial system. "At first, several lines of evidences surprisingly pointed to a possible increased neurogenesis in hypertension, as demonstrated by double Ki-67 and doublecortin (DCX) immunostaining in 13-week-old SHR and SHRSP rats compared to WKY." (PMID 31737062, 2019).
leiomyosarcoma (1 paper, 2023). An uncommon, aggressive malignant smooth muscle neoplasm, usually occurring in post-menopausal women. "Finally, DCX is an oncogene implicated in the uncontrolled migration of cancer cells, which is upregulated in UL and leiomyosarcomas." (PMID 36703136, 2023).
lung carcinoma (1 paper, 2023). "We applied GRF to simulation data and two real datasets: one involving the classification of two subtypes of lung cancer and the other involving the classification of doublecortin status in human embryonic stem cells." (PMID 37509188, 2023).
meningeal tumors (1 paper, 2011). "Expression of DCX in meninges has been observed in case of meningeal tumors." (PMID 22038821, 2011).
Osteochondroma (1 paper, 2019). A common, benign cartiliginous neoplasm arising from the metaphysis of bone. "In the context of the current patient, the presentation of multiple osteochondromas prevented the case being classified as solved upon detection of the partially diagnostic DCX variant but a less distinct phenotypic component may have avoided further investigation." (PMID 30632316, 2019).
ovarian carcinoma (1 paper, 2021). A malignant neoplasm originating from the surface ovarian epithelium. "Causal network analysis revealed novel pathways suggesting predicted inhibition of ovarian cancer through master regulator ASCL1 and dataset genes DCX, SEMA6B, HEY2, and KCNIP2." (PMID 35052372, 2021).
posttraumatic stress disorder (1 paper, 2022). "For example, inflammatory signals like interleukin 17A serum levels in a murine model of posttraumatic stress disorder modulate DCX and Ki67+cells in the DG or extracellular and adhesion molecules can promote alertness and activation of NSCs in response to indicators that affect the entire organism." (PMID 36407114, 2022).
progressive ataxia (1 paper, 2021). "Injuries, including spinal cord injuries (SCIs), progressive ataxia and brain stroke, were able to increase the number of meningeal-derived doublecortin (DCX)-positive immature neurons." (PMID 34638999, 2021).
Psoriasiform dermatitis (1 paper, 2024). A skin abnormality characterized by redness and irritation, with thick, red skin that displays flaky, silver-white patches (scales). "The number of DCX‐positive cells was significantly decreased in psoriasiform dermatitis mice (n = 7) compared with control mice (n = 5) (69.88 ± 0.778 vs. 98.33 ± 2.062, t = 14.620, p < 0.001)." (PMID 39660880, 2024).
stress-related disorder (1 paper, 2021). Stress-related disorders are mental health disorders that are a result of an atypical response to both short and long-term anxiety due to physical, mental, or emotional stress. "Although reported in a different neurogenic niche, their results indicate that the link between adult neurogenesis, DCX and stress-related disorders is far from clear and deserve further investigation." (PMID 34925362, 2021).
temporal lobe epilepsy (1 paper, 2018). A localization-related (focal) form of epilepsy characterized by recurrent seizures that arise from foci within the temporal lobe, most commonly from its mesial aspect. "DCX+ populations diminish with age in animals but studies have suggested seizure-enhanced maturation and proliferation of DCX+ cell types occurs in temporal lobe epilepsy (TLE) indicative of their underlying plasticity and responsiveness." (PMID 30005693, 2018). "We conclude that DCX identifies a range of morphological cell types in temporal lobe epilepsy, including immature populations, glial and microglial cell types." (PMID 30005693, 2018).
teratoma (1 paper, 2023). A non-seminomatous germ cell tumor characterized by the presence of various tissues which correspond to the different germinal layers (endoderm, mesoderm, and ectoderm). "To further validate the findings, we performed mIF staining of DCX in validation cohort (n = 7), and identified the positive correlations between the overall expression levels of DCX and teratoma grade." (PMID 36936909, 2023).
Thrombocytopenia (1 paper, 2025). A reduction in the number of circulating thrombocytes. "The pool of DCX+ cells remained unaffected by thrombocytopenia." (PMID 41286446, 2025).